HSPA5 (heat shock protein family A (Hsp70) member 5)
Diseases named in the same sentence as HSPA5 in open-access papers (continued):
Sharing a sentence is not in itself a finding about the gene and the disease.
renal fibrosis (9 papers, 2016 to 2025). A final common manifestation of a wide variety of chronic kidney diseases characterized by glomerulosclerosis and tubulointerstitial fibrosis. "In our research, although the HSPA5 expression was markedly elevated in renal fibrosis, resembling that in cancer diseases, its function was entirely distinct." (PMID 40255561, 2025). "This study elucidated a critical role of ERS-regulated HSPA5 in renal fibrosis through a comprehensive analysis of genetic and pharmacological experiments." (PMID 40255561, 2025). "The findings clarify the processes at play and suggest that focusing on HSPA5 may be a viable treatment approach to improve the longevity of tubular epithelial cells and reduce renal fibrosis in individuals with CKD." (PMID 40255561, 2025). "In conclusion, this research highlights the substantial involvement of HSPA5 in mediating ferroptosis, its role in the progression of EMT in renal fibrosis, and the interconnected relationship between ERS, a catalyst for ferroptosis, in the development of renal interstitial fibrosis." (PMID 40255561, 2025).
acute myeloid leukemia (8 papers, 2020 to 2025). Acute myeloid leukemia (AML) is a group of neoplasms arising from precursor cells committed to the myeloid cell-line differentiation. "For example, targeting cell surface expression of HSPA5 on acute myeloid leukemia (AML) blasts with CAR-T cells has shown promising anti-leukemic activity without affecting hematopoietic progenitor cells, indicating a potential therapeutic window." (PMID 40597436, 2025). "The expressions of HSPA5 were significantly decreased only in acute myeloid leukemia (LAML) (p<0.01)." (PMID 33767597, 2021).
Stroke (8 papers, 2011 to 2024). Sudden impairment of blood flow to a part of the brain due to occlusion or rupture of an artery to the brain. "Silencing of the transcription factor Forkhead box O1 (FoxO1) via the lncRNA GAS5/miR-378a-5p/Hspa5 axis in mice significantly improved neurological function recovery in intracerebral hemorrhage, which is the most devastating stroke subtype." (PMID 37987360, 2023).
colon adenocarcinoma (7 papers, 2020 to 2025). "HSPA5 expression was significantly upregulated in 14 types of cancer, including cholangiocarcinoma, colon adenocarcinoma, esophageal carcinoma, diffuse large B cell lymphoma, pancreatic adenocarcinoma, and others." (PMID 40429988, 2025).
glaucoma (7 papers, 2010 to 2022). Increased pressure in the eyeball due to obstruction of the outflow of aqueous humor. "HSPA5 levels have been shown to increase in tears in response to successful glaucoma treatment." (PMID 35216421, 2022).
oral squamous cell carcinoma (7 papers, 2014 to 2024). "Therefore, we believe that CD47 and HSPA5 have a feedback loop in OSCC cell lines, and suggest that CD47 mediates cancer progression through the HSPA5 signaling pathway in oral squamous cell carcinoma." (PMID 35678681, 2022).
osteoporosis (7 papers, 2014 to 2024). A condition of reduced bone mass, with decreased cortical thickness and a decrease in the number and size of the trabeculae of cancellous bone (but normal chemical composition), resulting in increased fracture incidence. "Also in the study of osteoporosis, in vitro studies showed that HSPA5 negatively regulated osteogenic differentiation, while inhibitor HA15 enhanced osteogenic differentiation." (PMID 38770048, 2024). "Alleles associated with slower heart rate (rs365990, MYH6), decreased risk of osteoporosis and short body height (rs2982570, ESR1), decreased risk of schizophrenia (rs1339227, RIMS1-KCNQ5) and decreased risk of anxiety and neuroticism (rs391957, HSPA5) were found to have higher frequency in LLIs." (PMID 39567526, 2024). "There seems to be no current research on the potential role of HSPA5 in osteoporosis, which would be an interesting direction." (PMID 36093072, 2022).
prion disease (7 papers, 2011 to 2023). A transmissible disease that is caused by a protein that is able to induce abnormal folding of normal cellular proteins, leading to characteristic spongiform brain changes, which are associated with neuronal loss without an inflammatory response. "Interestingly, two genes, HSPA5 and SOD1, involved in prion disease, which is also a neurodegenerative disease with pathogenesis similar to AD, were also enriched." (PMID 33250918, 2020).
retinal degeneration (7 papers, 2013 to 2025). Degeneration of the retina. "Depletion of seven genes (Eif2s1, Hspa5, Hspa8, Nploc4, Hyou1, Ufd1, and Vcp) showed an exacerbating effect on the Rho-Pro23His retinal degeneration compared to the Cas9+/− mice." (PMID 41282224, 2025). "Through protein–protein interaction (PPI) network analysis, six hub ferroptosis-related genes (Jun, Stat3, Hmox1, Atf3, Hspa5 and Ripk1) are ultimately identified in a mice model of retinal degeneration induced by light damage." (PMID 40299661, 2025).
thyroid cancer (7 papers, 2019 to 2025). "Using the Gene Expression Profiling Interactive Analysis (GEPIA) and Human Protein Atlas (HPA) datasets, the HSPA5 mRNA expression in different types of cancers and healthy tissues is high and the highest in thyroid carcinoma." (PMID 37275848, 2023). "But the levels of HSPA5 in LAML of paired normal tissue are much higher than that of the highest one in the thyroid carcinoma tissue." (PMID 33767597, 2021). "Metformin was discovered to upregulate heat shock protein family A member 5 (HSPA5, Bip), DNA damage-inducible transcript 3 (DDIT3, CHOP), and caspase-12 and induce endoplasmic reticulum stress and endoplasmic reticulum stress-associated apoptosis in vitro and in vivo in thyroid cancer." (PMID 37344841, 2023). "Previous studies in the literature, as well as our results, have detected reduced expression of the HSPA5 gene in thyroid cancer samples compared to non-neoplastic gland tissues." (PMID 40722651, 2025). "Other cancer types of tissues, except kidney chromophobe (KICH) and thyroid carcinoma (THCA), the expressions of HSPA5 were increased but not significantly." (PMID 33767597, 2021).
asthma (6 papers, 2023 to 2025). "Thus, HSPA5/A2M could be exploited as novel drug targets for childhood asthma while SQSTM1 might serve as a potential target or therapeutic responder." (PMID 41550933, 2025).
cholangiocarcinoma (6 papers, 2012 to 2026). A carcinoma that arises from the intrahepatic biliary tree (intrahepatic cholangiocarcinoma) or from the junction, or adjacent to the junction, of the right and left hepatic ducts (hilar cholangiocarcinoma). "By HDAC6 inhibition, the translocation of HSPA5 to the cell surface was blocked, thereby suppressing cell proliferation of cholangiocarcinoma." (PMID 37275848, 2023).
head and neck squamous cell carcinoma (6 papers, 2017 to 2025). A squamous cell carcinoma that arises from any of the following anatomic sites: lip and oral cavity, nasal cavity, paranasal sinuses, pharynx, larynx, and salivary glands. "According to analysis of Starbase website and Kaplan-Meier Plotter database, the expression of HSPA5 was significantly correlated with the occurrence of Head-neck squamous cell carcinoma (HNSC) and prognosis." (PMID 35342334, 2022).
HCMV infection (5 papers, 2017 to 2024). "Several of the PM proteins that were strongly upregulated during VACV infection were also upregulated at the cell surface during HCMV infection, including HSPA5, CALR and ERAP1." (PMID 35727847, 2022).
hyperlipidemia (5 papers, 2020 to 2025). "HSPA5 exhibited strong diagnostic potential in nephrolithiasis (AUC=1.000) and hyperlipidemia (AUC=0.920)." (PMID 40245021, 2025). "HSPA5 expression was higher in both the nephrolithiasis (P<0.001) and hyperlipidemia (P<0.01) groups compared to controls." (PMID 40245021, 2025). "Ultimately, the best common diagnostic biomarkers for nephrolithiasis and hyperlipidemia were identified as 3 diagnostic genes (HSP90AB1, HSPA5 and STUB1)." (PMID 40245021, 2025). "In hyperlipidemia, HSPA5 would contribute to lipid accumulation and metabolic dysregulation by influencing lipid metabolism-related signaling pathways including NF-κB and AMPK, as well as inflammatory responses." (PMID 40245021, 2025). "In addition, we validated the reliability of HSP90AB1, HSPA5, and STUB1 as diagnostic genes for nephrolithiasis and hyperlipidemia through external validation." (PMID 40245021, 2025). "Some attention has also been given to the relationship between HSPA5 and hyperlipidemia." (PMID 40245021, 2025). "Both diseases involve the crosstalk of HSPA5-mediated endoplasmic reticulum stress-inflammatory axis and oxidative stress, suggesting that HSPA5 serves as a key molecular link between nephrolithiasis and hyperlipidemia." (PMID 40245021, 2025). "In conclusion, HSPA5 may play a shared role in the pathogenesis of nephrolithiasis and hyperlipidemia by regulating endoplasmic reticulum stress, oxidative stress, and inflammatory responses." (PMID 40245021, 2025). "The same ROC analysis was performed for the hyperlipidemia group, with HSP90AB1 (AUC=0.777), HSPA5 (AUC=0.838), and STUB1 (AUC=0.877) also showing robust predictive performance." (PMID 40245021, 2025). "There were also only one upregulated (heat shock protein family A—Hspa5) and only one downregulated (apolipoprotein A1—Apoa1) hyperlipidaemia-dependent DEPs independent of strain and sex of mice with a similar pattern of changes in 8- and 28-week-old mice." (PMID 40240752, 2025). "Although the direct link between HSPA5 and kidney stones and hyperlipidemia are not yet fully confirmed, several researches propose that HSPA5 may play a role in the pathogenesis of these diseases." (PMID 40245021, 2025).
myositis (5 papers, 2010 to 2023). "Additionally, the biopsy specimens from patients with myositis and mice models of myositis demonstrated an increase in levels of Grp78 (also known as HSPA5), which is an ER stress-related protein." (PMID 29587702, 2018).
oropharyngeal carcinoma (5 papers, 2017 to 2025). Carcinoma, predominantly squamous cell, arising from the epithelial cells of the oropharynx. "In relation to oral and oropharyngeal cancer, significant associations were observed for a suite of genes including HSPA5, TNFAIP6, AKR1C1, CASP1, ANXA1, and MYC." (PMID 41023518, 2025).
tauopathy (5 papers, 2017 to 2024). Neurodegenerative disorders involving deposition of abnormal tau protein isoforms (tau proteins) in neurons and glial cells in the brain. "ER chaperone Hspa5 and small heat shock protein 22 (sHsp22) were found to improve the impairment in spatial learning and memory deficit in a mice Tauopathy model." (PMID 38648719, 2024). "These genes include Xbp1, Hspa5, Dnajc3, and members of the Pdi family, which overlap with C. elegans homologs in our transcriptomic dataset and are required for xbp-1s-mediated suppression of tauopathy." (PMID 39060347, 2024).
amyloidosis (4 papers, 2017 to 2023). A disorder characterized by the localized or diffuse accumulation of amyloid protein in various anatomic sites. "Both mRNA expression and protein levels of HSPA5 were higher in amyloidosis-induced mice compared with vehicle groups." (PMID 35099007, 2022). "The expression levels of Atg5 were not significantly different among any of the groups, and the levels of Hspa5 were upregulated in the amyloidosis-induced group without CR treatment (AL+F) but repressed by CR treatment (CR+F)." (PMID 28225824, 2017).
Anxiety (4 papers, 2022 to 2025). Intense feelings of nervousness, tension, or panic often arise in response to interpersonal stresses. "Another variant, T allele of rs391957 from HSPA5 gene, which is associated with decreased anxiety and neuroticism, was found to have high frequency in LLIs, with an odds ratio of 1.636 (95% CI: 1.26–2.125) for longer survival." (PMID 39567526, 2024). "Research studies found T allele of rs391957 from HSPA5 gene to be a protective factor for anxiety and neuroticism." (PMID 39567526, 2024).
Ataxia (4 papers, 2012 to 2025). Ataxia refers to impaired coordination of voluntary muscle movement. "Abnormal protein folding due to decreased rate of HSPA5 hydrolysis and disturbed SIL1-HSPA5 interaction is the cause of Marinesco-Sjogren syndrome that is characterized by ataxia, progressive myopathy and cataract." (PMID 22530004, 2012).
clear cell renal cell carcinoma (4 papers, 2017 to 2021). "It plays an onco-suppressive role in clear cell renal cell carcinoma by targeting HSPA5, which leads to inhibition of the progression of the disease, both in vitro and in vivo." (PMID 34572265, 2021).
diffuse large B-cell lymphoma (4 papers, 2021 to 2025). "On the other hand, EZH2 inhibitors impair the occurrence of ferroptosis by upregulating the heat shock protein family A member 5 (HSPA5) and stabilizing GPX4 in diffuse large B-cell lymphoma (DLBCL)." (PMID 39595619, 2024).
malaria (4 papers, 2010 to 2024). Malaria is a serious and sometimes fatal disease caused by a parasite that commonly infects a certain type of mosquito which feeds on humans. "Of relevance to the role of HSPs in human malaria pathogenesis, transcripts for HSP60 (HSPD1) were down-regulated in SMA (log2FC = −0.81), as were HSP70 family members: HSPA1A (−1.31), HSPA1B (−0.99), HSPA4 (−0.33), HSPA4L (−0.68), HSPA5 (−0.51), and HSPA6 (−0.81)." (PMID 39452740, 2024).
myocarditis (4 papers, 2011 to 2026). Myocarditis is a condition that is characterized by inflammation of the heart muscle (myocardium). "demonstrate that, in checkpoint inhibitor induced myocarditis, induction of ERβ leads to downregulation of MANF and HSPA5 in female mice to increase ICI‐myocarditis in females." (PMID 41580387, 2026).
osteoarthritis (4 papers, 2023 to 2025). A noninflammatory degenerative joint disease occurring chiefly in older persons, characterized by degeneration of the articular cartilage, hypertrophy of bone at the margins and changes in the synovial membrane. "For instance, SND1 promotes degradation of GPX4 by destabilizing HSPA5 mRNA and suppressing HSPA5 expression, thus promoting ferroptosis in osteoarthritis chondrocytes." (PMID 38286993, 2024).
sarcoma (4 papers, 2016 to 2021). A usually aggressive malignant neoplasm of the soft tissue or bone. "We next examined the expression of 19 genes in different bone-related sarcomas using The Cancer Genome Atlas (TCGA) database and found relatively high HSPA5 and ATF4 mRNA levels in tumor tissues and significantly low CBLC and RET expression levels." (PMID 31534554, 2019). "The similar results were observed in sarcoma samples from ONCOMINE database, and online survival analysis revealed that abnormal HSPA5 expression resulted in significantly shorter survival time compared to that maintained in lower level (HR = 1.77, P = 0.025)." (PMID 33291071, 2020).
scrapie (4 papers, 2010 to 2017). A fatal disease of the nervous system in sheep and goats, characterized by pruritus, debility, and locomotor incoordination. "In patients with sporadic CJD and in mice with scrapie, an increase in the levels of molecular chaperones such as GRP58, HSPA5 and HSP70 has been reported." (PMID 28431525, 2017).
Azoospermia (3 papers, 2019 to 2024). Absence of any measurable level of sperm,whereby spermatozoa cannot be observed even after centrifugation of the semen pellet. "In conclusion, eight hub genes, including EGFR, HSPA5, ATG3, KIAA0652, and MAPK1 were implicated in azoospermia." (PMID 36969237, 2023). "In the present study, functional analysis showed that HSPA5 might play a critical role in azoospermia." (PMID 36969237, 2023). "Functional similarity analysis showed that HSPA5 may play a key role in azoospermia." (PMID 36969237, 2023). "Functional similarity analysis showed that HSPA5 might play a key role in azoospermia." (PMID 36969237, 2023). "Functional similarity analysis revealed that HSPA5 may play a key role in azoospermia." (PMID 36969237, 2023).
chronic lymphocytic leukemia (3 papers, 2014 to 2023). "A prior study analyzed bone marrow samples from 10 patients with Waldenström's macroglobulinemia (WM), 12 with MM and 11 with chronic lymphocytic leukemia (CLL) to show that HSPA5 expression was increased relative to normal PCs obtained from healthy donors in these plasma cell disorders (GSE66910)." (PMID 25605012, 2015).
Cirrhosis (3 papers, 2011 to 2017). A chronic disorder of the liver in which liver tissue becomes scarred and is partially replaced by regenerative nodules and fibrotic tissue resulting in loss of liver function. "The rs430397 variant in glucose regulated protein 78 (GRP78 also known as HSPA5) has been associated with HCC and cirrhosis risk in Chinese populations with HBV infection." (PMID 27888630, 2016).
nephrolithiasis (3 papers, 2024 to 2025). The presence of a calculus in the pelvis of the kidney; this is most often composed of mineral salts and proteins. "In nephrolithiasis, HSPA5 may mediate renal tubular epithelial cell injury through endoplasmic reticulum stress, promoting calcium oxalate crystal deposition, while also exacerbating stone formation by modulating oxidative stress and the release of inflammatory cytokines." (PMID 40245021, 2025). "For nephrolithiasis biomarkers, the three pivotal genes, HSP90AB1 (AUC=0.857), HSPA5 (AUC=0.845), and STUB1 (AUC=0.872), showed strong predictive performance." (PMID 40245021, 2025). "Overall, studying HYOU1, HSPA5, and MANF could provide deeper insight into the role of ER stress in the pathogenesis of urolithiasis and their potential as novel targeted therapeutic approaches for nephrolithiasis." (PMID 39114033, 2024).
non-alcoholic fatty liver disease (3 papers, 2022 to 2023). "For example, HSPA5 could combine with pre-mRNA/mRNA transcribed from genes that encode for proteins playing a role in nonalcoholic fatty liver disease." (PMID 37156995, 2023).
pulmonary hypertension (3 papers, 2022 to 2025). Increased pressure within the pulmonary circulation due to lung or heart disorder. "Connectivity Map analysis identified more than 30 non-cancer indications, including known off-target uses (e.g., imatinib for pulmonary hypertension) and novel hypotheses (e.g., nilotinib for Alzheimer’s via HSPA5 modulation)." (PMID 40732226, 2025).
schizophrenia (3 papers, 2010 to 2024). A major psychotic disorder characterized by abnormalities in the perception or expression of reality. "Five genes (SELL, HLA-DRB1, CEBPD, HSPA5, and NRGN) from the matched list had been previously studied for schizophrenia with positive association signals, the rest of the genes were involved in immune responses or other neuronal diseases." (PMID 23282246, 2012). "Using the Haploview program, we tested the association of seven tagSNPs in gene GRB2 and two tagSNPs in gene HSPA5 in our Irish Case-Control Study of Schizophrenia (ICCSS) sample (1,021 cases and 626 controls)." (PMID 20613869, 2010).
skin cancer (3 papers, 2023). "Most importantly, HSPA5 was strongly expressed in human BCCs and SCCs, in particular in the invasively growing skin cancer cells, which showed low or no expression of NRF3 (areas indicated by white dotted lines)." (PMID 37807968, 2023).
thymoma (3 papers, 2021 to 2023). A neoplasm arising from the epithelial cells of the thymus. "Among the 33 cancer types, ACSL4 expression was most correlated with TMB in ACC, whereas FANCD2, HIF3A, HSPA5, and PSMB7 were most correlated with TMB in thymoma (THYM)." (PMID 35652069, 2022).
brain cancer (2 papers, 2016 to 2021). A primary or metastatic malignant neoplasm affecting the brain. "One-way ANOVA-based differential 2D-DIGE analysis identified significantly changed abundances of two P4HB, five CALR spots and one spot of HSPA5 in platelets between patients with lung and brain cancer and matched healthy controls." (PMID 34066760, 2021).